VDAC1 (voltage dependent anion channel 1)
Diseases named in the same sentence as VDAC1 in open-access papers (continued):
Sharing a sentence is not in itself a finding about the gene and the disease.
cancer (continued). "VDAC1 is also the most abundant and best studied isoform, and VDAC2 was reported as a pro-apoptotic protein, interacting with Bax, yet its effect in apoptosis is controversial, expressed mainly in cancer, but not in the brain." (PMID 34671273, 2021). "Since “cell death of cancer cells” was highlighted in Vdac1−/− MEF in the IPATM analysis, we investigated whether the lack of Vdac1 triggered apoptosis." (PMID 26322231, 2015).
tumor (140 papers, 2010 to 2026). "Transcriptomic analyses further showed that VDAC1 is significantly upregulated in tumor tissues and associated with unfavorable clinical outcomes." (PMID 42111501, 2026). "In contrast, factors like ATL3 (Log2 ratio 1.40), ERGIC1 (Log2 ratio 1.64), SPON1 (Log2 ratio 1.25), TNFAIP8 (Log2 ratio 1.99), and VDAC1 (Log2 ratio 1.20), associated with a “highly favorable” prognosis, suggest roles in tumor suppression." (PMID 39858632, 2025). "This study also provided an analysis of MSI or TMB associated with VDAC1 expression in different TCGA tumor types, providing clues for VDAC1-related tumor immunotherapy." (PMID 35958281, 2022). "For example, in uterine cervical cancer, high expression of VDAC1 was associated with exhibited deeper stromal invasion, larger tumor size, higher recurrence, and poorer overall survival." (PMID 33680287, 2021). "In tumor cells grown in hypoxia, this mitochondrial phenotype was previously linked to a C-terminal truncation of VDAC1 (VDAC1-ΔC form) with an apparent migration of 25 kDa on reducing SDS-PAGE gel." (PMID 29596470, 2018). "VDAC1-dependent MPT is an upstream mechanism playing a causal role in oxidative stress-induced apoptosis in tumor cells." (PMID 28524096, 2017). "Exposure to chrysin resulted in the decrease of the interaction between HK-2 and VDAC-1, which caused the release of pro-apoptotic proteins from mitochondrial and induced tumor cells to undergo apoptosis." (PMID 28320429, 2017). "Our results show that VDAC1 depletion caused a reversal of tumour-reprogramed metabolism that assaulted critical functional nodes in the oncogenic network, including arrested cell proliferation, and a reversal of cell properties to the non-oncogenic status, irrespective of the mutations carried." (PMID 30544833, 2018). "On the other hand, VDAC-1 sustains the high glycolytic rates of tumour cells by associating with hexokinase, and inhibits the formation of the mitochondrial permeability transition pore (MPTP) in the OMM, which is necessary for the release of pro-apoptotic factors." (PMID 27936075, 2016). "METHODS: Immunohistochemistry was performed in 43 previously molecularly and histologically classified PitNETs/adenomas on tumor and normal adenohypophyseal tissue for VDAC1 (porin) to assess mitochondrial density and the expression of OXPHOS-subunits." (PMID 41814071, 2026). "Additional strategies aim to disrupt mitochondrial function through VDAC1 blockade or to reduce tumor hypoxia using hypoxia-activated prodrugs, hyperbaric oxygen therapy, and oxygen-transporting agents." (PMID 41450919, 2025). "Seven GRPGs (PIM2, PGK1, ADPGK, YWHAZ, PTK2, PGAM1, and VDAC1) were significantly upregulated in the TCGA-BRCA tumor tissues." (PMID 40046063, 2025). "In previous studies, we showed that silencing human VDAC1 in an NSCLC xenograft mouse model inhibited tumor growth and altered oncogenic properties." (PMID 39272828, 2024). "Taken together, these results indicate that PLGA-PEI-si-m/hVDAC1-B given by i.v. is delivered to the lungs, and decreases VDAC1 expression, inhibiting cell proliferation and tumor growth." (PMID 39272828, 2024). "Our research has shown that treatment with si-VDAC1 leads to notable changes in the TME across various tumor types." (PMID 39456237, 2024). "The effects of reduced VDAC1 expression levels by si-m/hVDAC1-B treatment of the UM-UC3-derived tumors on tumor metabolism were analyzed following the expression levels of metabolism-related enzymes." (PMID 38607066, 2024). "It has been proposed that the dynamic changes in ΔΨm brought about by free tubulin in tumor cells are related to αβ-tubulin heterodimers that modulate VDAC1 conductance." (PMID 39334905, 2024). "Treatment with si-VDAC1 recognizing both murine and human VDAC1 (si-m/hVDAC1) led to metabolic reprogramming and subsequent inhibition of tumor growth." (PMID 39456237, 2024).
tumor (continued). "Next, the effect of VDAC1 silencing on the growth of UM-UC3 cell subcutaneous (s.c.)tumor xenografts established in nude mice was tested." (PMID 38607066, 2024). "In A549-derived tumors, silencing VDAC1 resulted in metabolic reprogramming, tumor regression, and significant alterations in the expression of thousands of genes, including TFs." (PMID 39456237, 2024). "Similar results with respect to bladder wall layers and tumor development can be seen when staining for VDAC1 expression." (PMID 38607066, 2024). "In order to verify the effect of VDAC1 on cell proliferation, tumor sections were stained with specific antibodies against the cell proliferation marker KI-67." (PMID 39272828, 2024). "We found that si-VDAC1 treatment effectively inhibited tumor growth in both subcutaneous and intracranial-orthotopic GBM mouse models." (PMID 39456237, 2024). "VDAC1 is involved in numerous biological processes, including tumor invasion, migration, metastasis, and proliferation." (PMID 36418670, 2023). "Depleting VDAC1 expression using short interfering RNA inhibit GB growth and tumor growth in xenograft mouse models." (PMID 37298093, 2023). "The tumors generated in the VDAC1 overexpression group (plvx-VDAC1) were considerably larger than those in the control group (plvx-Con), as measured by tumor volume." (PMID 36750173, 2023). "For the first time, it induced VDAC1 overexpression and VDAC1 oligomerization and inhibited tumor growth." (PMID 36900417, 2023). "VDAC1 depletion also reversed oncogenic properties and altered transcription factors, leading to tumor cell differentiation into neuron- and astrocyte-like cells." (PMID 37298093, 2023). "In particular, they show that, interestingly, AML is the only tumor type in which the VDAC1 gene is downregulated and its VDAC1P8 pseudogene is clearly up-regulated." (PMID 37344914, 2023). "And concerning the tumor phenotype, the interaction of VDAC1 with hexokinase (HK), the first glycolysis enzyme, grants the enzyme immediate access to newly synthesized ATP and confers protection from apoptosis." (PMID 37344914, 2023). "Specifically, the expression profile of VDAC1P1 and VDAC1P2 in this analysis largely mirrors that of VDAC1, in both healthy and tumor tissues." (PMID 37344914, 2023). "Herein, we investigated the potential roles of VDAC1 in tumorigenesis and progression based on the Cancer Genome Atlas (TCGA), Gene Expression Omnibus (GEO), and Clinical Proteomic Tumor Analysis Consortium (CPTAC) datasets." (PMID 35958281, 2022). "VDAC1 is a potential target for regulating apoptosis, both inducing apoptosis in malignant tumor cells and inhibiting apoptosis in neurogenerative diseases." (PMID 35686107, 2022). "Recent studies have demonstrated that some tumor-related signaling pathways alter the phosphorylation level of VDAC1, leading to cell metabolism rearrangement and affecting apoptosis and cell cycle regulation." (PMID 35958281, 2022). "The results show that silencing VDAC1 expression leads to reprogrammed metabolism and to multiple effects from tumor growth inhibition to modulation of the tumor microenvironment and inflammation, inducing differentiation of malignant cells." (PMID 35883451, 2022). "It has been reported that VDAC1, as the mitochondrial anchor site of HK, plays an essential role in maintaining the high glycolysis phenotype of tumor cells." (PMID 35958281, 2022). "The phosphorylation levels of VDAC1 between primary tumor tissues and normal tissues were compared based on the CPTAC." (PMID 35958281, 2022). "VDAC1 depletion leads to alterations in the expression of several thousands of proteins and affects the metabolism–epigenetics axis of the tumor, as the availability of substrates from the mitochondria to the nucleus for chromatin modifications is decreased." (PMID 35883451, 2022). "In this study, the increase in VDAC1 expression was also confirmed in most tumor tissues based on the analysis of TCGA and GTEx databases." (PMID 35958281, 2022).
tumor (continued). "Representative immuno-stained sections clearly showed marked increases in VDAC1 expression levels in the tumor tissues, relative to its levels in the healthy tissues." (PMID 35883451, 2022). "The upregulated HKDC1 leads to increased mitochondrial function through its binding with VDAC1, favoring glycolysis and tumor growth." (PMID 33423158, 2021). "The role of VDAC1 in PCa was confirmed by another study on PC-3 cells, where the silencing of VDAC1 expression led to the inhibition of both cell proliferation and tumour growth in xenografts." (PMID 34069262, 2021). "The question is why would this difference be caused in LMP1‐positive tumor cells and does LMP1 cause this change by directly regulating ANT1 or VDAC1." (PMID 34755470, 2021). "Regardless, because of the obvious relevance of apoptosis for tumor growth, VDAC1 has emerged as a candidate to develop VDAC1-targeting molecules." (PMID 34658929, 2021). "Tumor tissue lysates were immunoblotted with anti-VDAC1 antibodies recognizing both human and mouse VDAC1." (PMID 34200480, 2021). "By analyzing TCGA datasets, we observed that VDAC1 was overexpressed in CC specimens compared with non-tumor cervical specimens." (PMID 34224325, 2021). "We then demonstrated that knockout of Vdac1 expressing oncogenic RAS in murine embryonic fibroblasts (MEFs) potentiates tumor development in mice by promoting metabolic reprogramming, accelerating vascular destabilization and inflammation." (PMID 33238609, 2020). "We also explored the relationship between KMT2A and VDAC1 and their roles in the regulation of tumor growth in a mouse xenograft model." (PMID 32436862, 2020). "As a corollary, down-regulation of VDAC1 in tumor cells, with subsequent reduction in metabolite exchange between the mitochondria and cytosol, inhibited the growth of cells and tumors." (PMID 33114780, 2020). "Immunohistochemistry was performed to validate the effect of miR-197-3p mimics on tumor proliferation ability and the expression of Ki67, VDAC1, p-AKT and β-catenin." (PMID 32210729, 2020). "Reduction of VDAC1 expression by a specific miRNA, miR320a, promoted mitophagy in serum starved cervical cancer cells and blocked tumor cell proliferation and invasion in NSCLC, both in vitro and in vivo." (PMID 33114780, 2020). "We also showed that the knockout of Vdac1 in murine embryonic fibroblasts (MEFs) expressing oncogenic RAS potentiates tumor development in mice by promoting metabolic reprogramming, accelerating vascular destabilization and inflammation." (PMID 32194829, 2020). "Interactions between VDAC1 and the anti-apoptotic proteins Bcl-2, Bcl-xL, and HK protect tumor cells from apoptosis." (PMID 33114780, 2020). "Tumor cells expressing VDAC1 and containing VDAC1-ΔC had an upregulation of metabolism (both oxidative phosphorylation (OXPHOS) and glycolysis) and were resistant to apoptosis driven by staurosporine or etoposide." (PMID 33238609, 2020). "We show that delivery of Tf-D-HKC8 peptide dissociates HKDC1 from VDAC1, induces mitochondrial dysfunction and oxidative stress, and subsequently suppresses tumor growth." (PMID 32203147, 2020). "We demonstrated here that VDAC1 depletion leads to metabolism reprograming, that in turn regulates epigenetically-related enzymes, and hence gene transcription, leading to tumor reprograming, including growth inhibition and cell differentiation." (PMID 32331482, 2020). "Following GBM tumor treatment with si-RNA specifically targeting human VDAC1, not only were the levels of VDAC1 decreased but so were those of TSPO." (PMID 31288390, 2019). "Significantly higher VDAC1 expression was observed in the tumor center compared to adjacent normal tissue (p < 0.0001)." (PMID 31167495, 2019). "This points to reduced transport and trafficking activity following a long period of tumor VDAC1 depletion." (PMID 31661894, 2019).
tumor (continued). "The results show that tumor treatment with si-RNA against human VDAC1 resulted in tumor microenvironment reprograming, leading to reduced stromal activity essential for tumorigenesis and inflammation." (PMID 31661894, 2019). "Using a subcutaneous (s.c.)or intracranial-orthotopic GBM model, we showed that that silencing the expression of human VDAC1 using si-hVDAC1, dramatically decreased tumor growth." (PMID 31661894, 2019). "HKDC1 expression potentiates the permeability transition pore by interacting with VDAC1, subsequently increasing glucose uptake and promoting cell proliferation and tumor growth." (PMID 31058090, 2019). "In contrast to the reprograming of metabolism and the elimination of CSCs that was already observed following the relatively short-term treatment with si-hVDAC1, differentiation was obtained only after a long period of the tumor cells being depleted of VDAC1." (PMID 31661894, 2019). "HKDC1 is located on the mitochondrial membrane and regulates the permeability transition pore opening by binding with VDAC1, subsequently modulating glucose uptake, cell proliferation, and tumor growth." (PMID 31058090, 2019). "In the present study, using immunohistochemistry, immunoblotting, quantitative real-time PCR (qRT-PCR) and proteomics profiling by mass spectroscopy, we demonstrate that tumor reprograming is dependent on the duration that the tumor was depleted of VDAC1." (PMID 31661894, 2019). "Here, we showed that VDAC1 silencing in A549 cell-derived tumours resulted in reduced expression of lung-specific CSC markers, such as ALDH1, KLF4, SOX2, CD133, CD44, CD144, EPCAM, Oct3/4 and Nanog." (PMID 30544833, 2018). "Recently, the C-terminal truncation of the VDAC1 isoform, termed VDAC1-ΔC, has been observed in chemoresistant late-stage tumor cells grown under hypoxic conditions with activation of the hypoxia-response nuclear factor HIF-1α." (PMID 29596470, 2018). "After the mice were sacrificed, the tumours were excised and frozen or fixed in formalin and sections were IHC-stained for VDAC1 expression." (PMID 30544833, 2018). "Hexokinase II (HK-II), overexpressed in tumor cells and required for tumor initiation and tumor growth in mouse models, binds to VDAC1." (PMID 28168164, 2017). "Our results suggest that VDAC1-based peptides have multiple effects, including perturbing cell energy homeostasis, inhibiting tumor growth, stemness and inducting apoptosis." (PMID 28412744, 2017). "This ensured that MJ dissociated the combination of HK2 and VDAC1 to block energy for tumor growth by inhibiting glycolysis." (PMID 28498814, 2017). "We have demonstrated that downregulation of VDAC1 expression by hVDAC1-shRNA disrupts energy production, arrests cell growth, and inhibits tumor development in an animal model, illustrating the essential role of VDAC1 in energy production and cell growth." (PMID 28824871, 2017). "We also confirmed that the protein level of VDAC1 was decreased in miRNA mimics transfected tumor cells group compared to NC group when overexpressing miR-320a." (PMID 27304056, 2016). "Further we show that MiR-320a was significantly decreased in NSCLC tissues compared with adjacent non-tumor tissues, and MiR-320a level is negatively correlated with VDAC1 in NSCLC tissues by Pearson's correlation coefficient analysis." (PMID 27304056, 2016). "We found the protein level of VDAC1 was decreased in miRNA mimics transfected tumor cells group compared to NC group when overexpressing miR-320a." (PMID 27304056, 2016). "In this paper, we identified Mps1 as a novel regulator of VDAC1; Mps1 binding to VDAC1 can attribute to tumor cell survival by regulating cytochrome c release." (PMID 27383047, 2016). "Anchoring of HKI/II is probably involved in the exacerbated metabolism of tumor cells in hypoxia in the presence of VDAC1-ΔC." (PMID 27625993, 2016).